MIR219A2 (microRNA 219a-2)
Synonyms: hsa-mir-219-2; MIR219-2; MIRN219-2; hsa-mir-219a-2; mir-219a-2
Gene: MicroRNA gene on chromosome 9 (128,392,618 to 128,392,714, reverse strand). Ensembl gene ENSG00000284185.
Gene Ontology:
Biological process: miRNA-mediated post-transcriptional gene silencing
Cellular component: RISC complex
Homologues: Orthologues: chimpanzee ptr-mir-219-2 (100% identical), macaque mml-mir-219-2 (100% identical), pig MIR219A2 (100% identical), mouse Mir219a-2 (99% identical), rabbit MIR219A2 (96% identical), tropical clawed frog xtr-mir-219 (68% identical), dog MIR219-2 (67% identical), zebrafish mir219-3 (58% identical), Drosophila melanogaster mir-219 (51% identical). Paralogues in human: MIR219B (57% identical).